BOD1 (biorientation of chromosomes in cell division 1)
Description:
Required for proper chromosome biorientation through the detection or correction of syntelic attachments in mitotic spindles.
Synonyms: FAM44B
Tractability: PROTAC: ubiquitination databases record sites on it.
Gene: Protein-coding gene on chromosome 5 (173,607,145 to 173,616,659, reverse strand). Ensembl gene ENSG00000145919.
Subcellular location: Cytoplasm, cytoskeleton, microtubule organizing center, centrosome; Chromosome, centromere, kinetochore
Pathways (Reactome):
Gene expression (Transcription): Formation of WDR5-containing histone-modifying complexes
Gene Ontology:
Molecular function: protein binding; protein phosphatase 2A binding; protein phosphatase inhibitor activity
Biological process: mitotic metaphase chromosome alignment; mitotic sister chromatid biorientation; mitotic sister chromatid cohesion, centromeric; protein localization to chromosome, centromeric region
Cellular component: centrosome; outer kinetochore; Set1C/COMPASS complex; spindle microtubule; spindle pole; nucleoplasm
Genetic constraint (gnomAD): Loss-of-function variants: 11 observed, 13.63 expected, observed/expected ratio (o/e) 0.81, 90% interval 0.51 to 1.34. The upper end of that interval is the gene's LOEUF score, 1.34, which puts it in group 5 of 6, group 1 being the genes least tolerant of losing a copy. Missense variants: 182 observed, 203.69 expected, observed/expected ratio (o/e) 0.89, 90% interval 0.79 to 1.01. Synonymous variants: 105 observed, 83.31 expected, observed/expected ratio (o/e) 1.26, 90% interval 1.08 to 1.48.
Homologues: Orthologues: chimpanzee BOD1 (100% identical), macaque BOD1 (99% identical), dog BOD1 (94% identical), mouse Bod1 (85% identical), rat Bod1 (85% identical), tropical clawed frog bod1 (71% identical). Paralogues in human: BOD1L2 (80% identical), BOD1L1 (55% identical).
Diseases named in the same sentence as BOD1 in open-access papers:
BOD1 is named in the same sentence as 13 diseases in open-access papers, as found by Europe PMC text mining. Sharing a sentence is not in itself a finding about the gene and the disease. The quoted sentences say what the papers report.
Ataxia (2 papers, 2022 to 2025). Ataxia refers to impaired coordination of voluntary muscle movement. "Together, our data indicate that BOD1 plays an important role in the function of PCs and that disruption of the IV/V lobePCs → FNCaMKIIα+ circuit by BOD1 deficiency mediates ataxia-like behavior in mice." (PMID 35641478, 2022). "To determine whether the BOD1 deficiency in PCs could induce ataxia, we generated conditional knockout mice in which BOD1 was selectively ablated in cerebellar PCs." (PMID 35641478, 2022). "Intriguingly, overexpression of BOD1 locally in the IV/V lobe increased the firing frequency of PCs, improved ataxia-like behaviors, and augmented dendritic maturation in L7-Cre; BOD1f/f mice." (PMID 35641478, 2022).
cognitive decline (1 paper, 2024). "Consistently, HFS inhibited cognitive decline in Bod1-deficient and PD mice." (PMID 39359881, 2024).
Cognitive impairment (1 paper, 2016). Abnormal cognition is characterized by deficits in thinking, reasoning, or remembering. "Although our data strongly indicate a post-mitotic role of Bod1, subtle mitotic defects in neurogenesis may also contribute to the cognitive impairment of individuals carrying BOD1 mutations." (PMID 27166630, 2016).
Intellectual disability (1 paper, 2016). "Here we report a stop-mutation in the BOD1 (Biorientation Defective 1) gene, which co-segregates with intellectual disability in a large consanguineous family, where individuals that are homozygous for the mutation have no detectable BOD1 mRNA or protein." (PMID 27166630, 2016).
microcephaly (1 paper, 2016). A congenital or acquired developmental disorder in which the circumference of the head is smaller than normal for the person's age and sex. "Like homozygous carriers of BOD1 mutations, individuals affected by HCFC1 mutations show no microcephaly phenotype." (PMID 27166630, 2016).
cancer (5 papers, 2016 to 2021). A tumor composed of atypical neoplastic, often pleomorphic cells that invade other tissues. "When performing GSEA for canonical pathways using the C2 gene set, we found that some lncRNAs, including lnc-BOD1-1:7, -1:8, and -1:9, as well as lnc-GCH1-2:1, -2:2, and -2:3 were associated with many immune- and cancer-associated pathways." (PMID 31810243, 2019). "Taken together, these results suggest that radiation alters miR-142-3p and Bod1 expression in carcinoma cells, and thus contributes to early stages of radiation-induced genomic instability." (PMID 27527863, 2016). "Because Bod1 knockdown induced premature chromatid separation and sensitized carcinoma cells to X-rays, we investigated whether Bod1 overexpression also affected irradiation-induced premature chromatid separation and radiosensitivity." (PMID 27527863, 2016). "In the 20 cases analyzed, we detected three fusion events in known cancer driver genes (ATM in LUSC2; PTEN in LUSC1; WHSC1 in LUSC1), and a further seven events in candidate tumor-suppressor genes, including BOD1, DLG2, MBD2, and RBL1." (PMID 30348992, 2019).
infection (2 papers, 2021 to 2025). The state of being infected such as from the introduction of a foreign agent such as serum, vaccine, antigenic substance or organism. "For instance, among the genes upregulated in infected wild‐caught birds reported here, RAB20 was also upregulated in 'amakihi surviving experimental infection, and three upregulated genes (COG5, BOD1, and PCDH10 which activates PCDHGA6) were downregulated in 'amakihi that perished." (PMID 40909016, 2025).
tumor (2 papers, 2019). "For half of the downregulated lncRNAs, namely lnc-ACSBG2-1:1 and lnc-BOD1-1:7, -1:8, and -1:9, high lncRNA expression levels correlated with primary therapy outcome success and lower tumor grade, which further suggest potential tumor-suppressing roles." (PMID 31810243, 2019). "Eight downregulated lncRNAs—lnc-ACSBG2-1:1; lnc-ANKRD54-1:1; lnc-BOD1-1:7, -1:8, and -1:9; and lnc-MUC22-1:1, -1:7, and -1:8—demonstrated correlation between lower patient survival rate with lower expression of lncRNA, indicating a potential tumor-suppressing role for these lncRNAs." (PMID 31810243, 2019).
BOD1 also shares sentences with these, for which no sentence is quoted: schizophrenia (2 papers); autism (1); breast carcinoma (1); hepatocellular carcinoma (1); triple-negative breast carcinoma (1).